E2F1 (E2F transcription factor 1)
Diseases named in the same sentence as E2F1 in open-access papers (continued):
Sharing a sentence is not in itself a finding about the gene and the disease.
breast carcinoma (continued). "To confirm that miR-20b-5p regulated CCND1 and E2F1 expression, we performed three experiments, namely, a comparison between BCSCs and the control breast cancer cells, a dual-luciferase assay and western blot analysis after overexpression or knockdown of miR-20b-5p." (PMID 33008330, 2020). "In vitro and in vivo studies demonstrated the anti-breast cancer activities of eugenol, suggesting that it could be used to enhance breast cancer treatment by targeting the E2F1/survivin pathway." (PMID 32019140, 2020). "In breast cancer, miR-1258 can target and downregulate the expression of E2F1." (PMID 32733928, 2020). "Furthermore, the transcription factor E2F1 bound with the promoter region of Nanog gene to promote its transcription and facilitate the breast cancer stemness and tumorigenesis." (PMID 32039833, 2020). "Direct interaction between RIP140 and E2F1 in breast cancer cell lines results in a repression of E2F1 target genes and could regulate cell proliferation." (PMID 32157438, 2020). "Interestingly, the correlation between ER and E2F1 in breast cancer cell line is a controversial issue." (PMID 32742594, 2020). "Thus, further investigations should be performed to validate the potential application of E2F1 on breast cancer gene therapy." (PMID 31278126, 2019). "The microRNA and its target were important regulatory mechanism for LINC00511, such as miR-185-3p/E2F1 in breast cancer, miR29b-3p/VEGFA in pancreatic cancer, miR-15a-3p/Wnt signaling pathway in bladder cancer, miR-765/APE1 in osteosarcoma and miR-765/LAMC2 in tongue cancer." (PMID 31434692, 2019). "By taking the advantage of the highly proliferative property of breast cancer, a novel recombinant adenovirus which could selectively kill tumor cells is established under an E2F-1 promoter." (PMID 31278126, 2019). "These achieved data demonstrated that E2F-1 may serve as a potential target for breast cancer gene therapy." (PMID 31278126, 2019). "Together these data led to the hypothesis that Fgf13 is critical for breast cancer metastasis, and that upregulation of Fgf13 may partially explain how E2F1 promotes breast cancer metastasis." (PMID 31341204, 2019). "Moreover, the overexpression of E2F-1 has been reported to have a prognostic value in breast cancer." (PMID 30970566, 2019). "Additionally, E2F1 is highly expressed in breast cancer, contributing tumor cell proliferation and predicts poor prognosis." (PMID 31278126, 2019). "Furthermore, proper levels of cyclin dependent kinases (CDKs) and cyclins, including D-type cyclins critical for E2F1 activation, were dependent on K19 expression, and K19-cyclin D co-expression was observed in human breast cancer tissues." (PMID 31601969, 2019). "In addition, this analysis has also identified a new role for the E2F1 target gene fibroblast growth factor 13 (Fgf13) in breast cancer metastasis." (PMID 31341204, 2019). "Estrogen receptor alpha could mediated proliferation of human breast cancer via a p21/PCNA/E2F1-dependent pathway." (PMID 31409371, 2019). "In addition, a novel recombinant adenovirus has been constructed that targeted E2F-1 and expressed IL-15, and validated its inhibitive effect on breast cancer cells, providing new experimental basis for breast cancer gene therapy." (PMID 31278126, 2019). "The LINC00511/miR-185-3p/E2F1/Nanog axis may have therapeutic potential for breast cancer stemness and tumorigenesis." (PMID 30482236, 2018). "In addition, Hossain et al48 confirmed that miR-17 down regulates E2F1 expression in breast cancer cells." (PMID 30013305, 2018). "Low expression of E2F1 significantly correlates with favorable breast cancer outcomes." (PMID 29633513, 2018).
breast carcinoma (continued). "Similarly, we found that E2F1 mRNA expression was increased in breast cancer cells MDA-MB-231, and MCF-7 and up-regulated in the miR-185-3p inhibitor transfection and enhanced LINC00511 plasmid transfection." (PMID 30482236, 2018). "The increase in E2F in copy number of the region could enhance the affinity of SMYD3 and E2F-1 and increase the possibility in occurrence of breast cancer and poor prognosis." (PMID 29089464, 2018). "Aberrant regulation of E2F1/cyclin/CDK2 promotes tumor progression in breast cancer." (PMID 29633513, 2018). "Also, silencing E2F1 or E2F3 in Her2+ breast cancer cells suppresses centrosome amplification, while overexpression of E2F1, E2F2, or E2F3a in MCF10A cells is sufficient to trigger centrosome amplification and chromosome instability." (PMID 30381801, 2018). "Similarly to GTSE1, HMMR is regulated by both TEAD4 and E2F1 and has a critical role in breast cancer cell migration." (PMID 28978043, 2017). "The data suggest that MALAT activates the CDK4/E2F1 signaling pathway in breast cancer." (PMID 26918449, 2016). "Interestingly, most of these key repair genes, including BRCA1, RAD51, RAD54L and BLM, were also identified in this study as E2F1 targets in breast cancer." (PMID 27666291, 2016). "Thus, our findings provided new insights into the mechanism of breast cancer cell proliferation modulated by MALAT1-miR-124 -CDK4/E2F1 signaling pathway in the development of breast cancer." (PMID 26918449, 2016). "Moreover, it was experimentally shown in breast cancer cells that Rb indirectly suppresses H19 expression by repressing E2F1, while in colorectal cancer cells and in hepatocellular carcinoma cells, H19 derived miR-675 negatively regulates Rb expression." (PMID 26536864, 2015). "Therefore, we demonstrated that the simultaneous targeting of DNA and E2F1 methylation was an effective epigenetic treatment to induce apoptosis in breast cancer cells." (PMID 25064027, 2014). "We identify a novel interaction between HES6 and E2F1 and E2F1 and the AR and show enhancement of E2F1 activity that seems to result from protein complex formation rather than increased E2F1 expression as previously found in breast cancer." (PMID 24737870, 2014). "Among its dysregulated genes, CCND2 is differentially expressed between breast cancer patients with bone metastases and other patients; E2F1 can regulate DZ13 to induce a cytotoxic stress response in tumour cells metastasizing to bone; TGFB2 is related to the bone metastases development." (PMID 25163697, 2014). "Because oestrogen receptor α (ERα) regulates E2F1 expression to mediate tamoxifen resistance in ERα-positive breast cancer cells, we aimed to define the possible roles of ERα and E2F1 in promoting the resistance of ERα-negative breast cancer cells to 4-hydroxy-tamoxifen (4OHT)." (PMID 25064027, 2014). "Eugenol could constitute a potent anti-breast cancer agent with less side effects than the classical chemotherapeutic agents, through targeting the E2F1/survivin oncogenic pathway." (PMID 24330704, 2013). "Therefore, eugenol targets several breast cancer-related signaling pathways, leading to strong inhibition of two important breast cancer oncogenes E2F1 and survivin in both luminal as well as basal like breast cancer cell lines." (PMID 24330704, 2013). "Indeed, specific down-regulation of E2F1 strongly reduced the level of survivin and increased the effect of eugenol on breast cancer cells." (PMID 24330704, 2013). "The results presented in this study suggest a dynamic interplay between methylation and other posttranslational modifications of E2F1 in breast cancer cells, in which the in vivo levels of methylated and unmethylated E2F1 are determined by the opposing actions of Set9 and LSD1." (PMID 23251702, 2012). "Our analyses revealed that KIAA0191 transcript abundance could be used in the context of average to high levels of E2F1 transcripts to more precisely predict breast cancer patient survival." (PMID 21453498, 2011).
breast carcinoma (continued). "To verify that E2F1 expression correlated with patient survival in large microarray breast cancer datasets, we made use of a database comprising a cohort of 295 breast cancer patients, whose tumors' gene expression profiles are known and for which clinical follow up data is available." (PMID 21453498, 2011). "However, in the context of average to high expression of E2F1 transcript levels, high KIAA0191 expression was linked to poor breast cancer patient prognosis, whereas low KIAA0191 expression was linked to good outcome for these patients." (PMID 21453498, 2011). "Indeed, such genes would be useful for increasing the accuracy of genomic based clinical outcome predictors, as well as understanding E2F1 based proliferation programs in breast cancer cells." (PMID 21453498, 2011). "E2F-1 has been studied as a potential marker in breast cancer diagnostics." (PMID 19891787, 2009). "This hypothesis was based on a previous study showing an interaction between DDB2 and the transcription factor E2F1, a proliferative marker in breast carcinoma." (PMID 18431487, 2008). "We obtained similar results when E2F1 levels were compared with the breast cancer intrinsic subtypes, with the recurrence score and with the wound response signature, all of these gene expression-based predictors being reported by Fan and colleagues in the NKI data set." (PMID 17535433, 2007). "We investigated whether mRNA levels of E2F1, a key transcription factor involved in proliferation, differentiation and apoptosis, could be used as a surrogate marker for the determination of breast cancer outcome." (PMID 17535433, 2007). "We explored the extent to which experimental validation of binding sites might alter our results by replacing connectivity data for the breast cancer subsets with ChlP-on-chip data for three TFs (Myc and E2F1), for which ChlP-on-chip data were available." (PMID 16670008, 2006). "It is interesting to note that whereas E2F1 is up-regulated in breast tumors, its expression is low in prostate tumors, which typically have genomes with fewer copy number changes than most ductal invasive breast cancers." (PMID 16620391, 2006). "Similarly, previous reports have showed that E2F1 could bind to the promoter of DNMT1 (encoding a DNA methyltransferase), and upregulate DNMT1 expression resulting in breast cancer cell proliferation." (PMID 39957240, 2025). "Thus, the LINC00511/miR-185-3p/E2F1/Nanog axis may also have therapeutic potential, by regulating breast cancer stemness and tumorigenesis." (PMID 40951838, 2025). "Additionally, RPL5 downregulated E2F1, which was overexpressed in breast cancer cells." (PMID 35293275, 2022). "In addition, activation of miR-185-3p/E2F1/Nanog axis could strengthen the invasiveness of breast cancer." (PMID 35030974, 2022). "For example, E2F1 could facilitate breast cancer carcinogenesis by promoting cirSEPT9 biogenesis." (PMID 35563733, 2022). "Taken together, these results of in vitro and in vivo studies demonstrate that SEC61G promotes breast cancer development and metastasis via modulating glycolysis and is transcriptionally regulated by E2F1, which might be utilized as a promising therapeutic target of breast cancer treatment." (PMID 34039955, 2021). "Furthermore, to investigate whether E2F1 follows a similar expression pattern in breast cancer as ESRP1, we analyzed TCGA database and observed that E2F1 is significantly upregulated in primary tumors compared to normal tissues." (PMID 34362878, 2021). "The D-Arg PEP targeting activator family members of transcription factor E2F— namely, E2F-1, E2F-2, and E2F-3a—showed a synergistic anti-cancer effect when used in combination with chemotherapeutic drug cisplatin against the prostate cancer, breast cancer, and lymphoma cell lines." (PMID 33652640, 2021). "Thus, SEC61G could antagonize the effect of E2F1 knockdown in regulating breast cancer cell proliferation, invasion, and apoptosis." (PMID 34039955, 2021).
breast carcinoma (continued). "The transcriptional factor E2F-1 plays a significant role in the control of cell cycle, proliferation and carcinogenesis, and it is higher expressed in breast cancer tissues compared with normal tissues, suggesting that E2F-1 may be an effective target for treatment." (PMID 33574894, 2020). "We found that a moderate SMF (~150 mT) accelerated cell proliferation but inhibited breast cancer cell migration and shortened telomere length, which was associated with decreased telomerase activity and expression of TERT, as well as corresponding upregulation of e2f1 expression." (PMID 32462015, 2020). "Furthermore, overexpression of E2F1 in MDA-MB-468 breast cancer cells induces apoptosis." (PMID 33291686, 2020). "MALAT1 via miR-124/CDK4/E2F1 axis could enhance breast cancer progression." (PMID 33330110, 2020). "This suggested that the E2F1 target genes altered in these tumors are associated with human breast cancer metastatic potential and highlights that E2F1 may be a master regulator of breast cancer metastasis since it controls the expression of multiple pro-metastatic genes." (PMID 31341204, 2019). "Therefore, miR-20 is a strong candidate for targeting E2F1 mRNA in breast cancer." (PMID 30013305, 2018). "Importantly, previous studies have shown that elevated expression of upregulated genes in the E2F1 and E2F2 signature genes are associated with decreased time to distant metastasis free survival in breast cancer patients compared to those with low expression of these genes." (PMID 29617434, 2018). "Since TFDP3 represses the transcriptional activity of downstream genes by preventing the E2F1 heterodimer from entering the nucleus, we speculated that the expression of TFDP3 in breast cancer would cause transcriptional repression of certain genes downstream of E2F1." (PMID 28114432, 2017). "Moreover, the present study elucidated the MALAT1-miR-124-CDK4/E2F1 signaling pathway in breast cancer, which might provide a new approach for tackling breast cancer." (PMID 26918449, 2016). "Notably, depletion of HER2 rescued the breast cancer cells from 5a-induced E2F1 downregulation and also abrogated the effect of 5a on the activation of caspase-7, caspase-3 and PARP, suggesting that HER2 is the predominant target for 5a-induced cell cycle arrest and apoptosis." (PMID 25766325, 2015). "Thus, through repressing both AIB1 and E2F1, miR-17-5p may “kill two birds with one stone” in reducing breast cancer cell proliferation." (PMID 24013378, 2013). "Notably, low E2F1 levels were related to favorable breast cancer outcome." (PMID 24330704, 2013). "Interestingly, AIB1 functions as a coactivator of E2F1 to promote breast cancer cell proliferation." (PMID 24013378, 2013). "Eugenol exhibits anti-breast cancer properties both in vitro and in vivo, indicating that it could be used to consolidate the adjuvant treatment of breast cancer through targeting the E2F1/survivin pathway, especially for the less responsive triple-negative subtype of the disease." (PMID 24330704, 2013). "In addition to the promising therapeutic properties of the TMCG/DIPY combination, we described in this study a coordinate mechanism by which simultaneous demethylation of DNA and E2F1 contributes to the reactivation of the tumour suppressor RASSF1A in breast cancer cells." (PMID 23251702, 2012). "Taken together, these data suggest that up-regulation of the expression of the tumour-suppressor genes (р53, BRCA1, SYK) and transcription factor E2F1 could be responsible for the antimitotic effect of D-glucuronyl C5-epimerase in human breast cancer cells in vitro." (PMID 20723247, 2010).
breast carcinoma (continued). "However, hypothesis of this study was that DDB2 could play a role in breast cancer cell growth, resulting in its well known interaction with the proliferative marker E2F1 in breast neoplasia." (PMID 18431487, 2008). "We then investigated the roles of c-Myc and E2F1 in the synergistic effect of FB23 and ibrutinib on the progression of breast cancer." (PMID 41281757, 2025). "In breast cancer cells, BRD4 methylation specifically determines the recruitment of the TF E2F1 to selected target genes." (PMID 40809945, 2025). "In the lung metastasis model of breast cancer, the combination of FB23 and ibrutinib led to a significant reduction in the protein expression levels of c-Myc and E2F1, as well as the mRNA expression levels of c-Myc in MDA-MB-231LMF3 and BT-549LMF3 cells." (PMID 41281757, 2025). "We also observed a positive correlation between the expression of XBP1s and E2F1, as well as E2F1 targets in tumors obtained from patients with HR+/HER2− early breast cancer." (PMID 40940685, 2025). "Based on in vivo and in vitro studies, we revealed that XBP1s enhanced the expression of E2F1 target genes by transcriptional activation of SND1, thereby exerting a pro‐survival effect in patients with HR+/HER2− breast cancer receiving the combined therapy." (PMID 40940685, 2025). "While the interaction between E2F1 and EZH2 in the activation of oncogenic pathways has been observed in other cancers, their collaborative role in breast cancer, especially in TNBC, remains largely unexplored." (PMID 41413688, 2025). "HBV infection lead to increased expression levels of several key genes in breast cancer cell lines, including CDK2, PCNA, CCNE2, CXCL8, E2F1, and CASP3." (PMID 40697521, 2025). "Mechanistically, we found that CDCA5 promoted the binding of E2F transcription factor 1 (E2F1) to FOXM1 promoter, and Wnt/β-catenin signaling was required for CDCA5 induced development of breast cancer." (PMID 38978058, 2024). "Analysis of microarray data using the KM Plotter tool showed that overexpression of ATAD2, E2F1, and FOXM1, each conferred significantly poorer recurrence-free survival in breast cancer patients." (PMID 39335162, 2024). "It has been reported that the DDX5 locus is frequently amplified in breast cancers and that over-expressed DDX5 facilitates cell growth by directly binding to E2F1 to increase the expression of E2F target genes involved in DNA replication." (PMID 39769018, 2024). "Subsequent research showed that miRNA-205, present in the exosomes, directly silenced the E2F transcription factor 1 (E2F1) target gene, thereby promoting tamoxifen resistance and tumorigenesis in breast cancer." (PMID 38691224, 2024). "In breast cancer cells, E2F7 competes with E2F1 for binding to the promoter of its target gene, deleted in lymphocytic leukemia 2 (DLEU2)." (PMID 39613162, 2024). "We also found that PCK2 promoted cell cycle progression, particularly the G1/S transition, and induced upregulation of E2F1, cyclin D1, cyclin D2, and CDK4 in ER+ breast cancer cells." (PMID 35757841, 2023). "Briefly, the ER + breast cancer cell lines, T47D and ZR75, were co-transfected with the NNAT promoter-reporter construct, and plasmids that constitutively expressed E2F1, E2F4, NRF1, PPARα/RXR, PPARγ/RXR, or control (pLX304)." (PMID 37400769, 2023). "For instance, Detection of epigenetic regulators, such as ZMYND8, E2F1 and KDM6A, would be beneficial for determining prognosis and management in breast cancer patients." (PMID 36967443, 2023). "Our study has made groundbreaking progress in identifying key transcription factors, such as SP1, E2F1, and SIN3A, as well as kinases, including MAPK14, CSNK2A1, and CDC2, whose role in breast cancer progression is paramount." (PMID 38084295, 2023). "Elevated E2F1 levels activate cell cycle progression and KIF26A expression, thereby promoting the proliferation of breast cancer cells." (PMID 37965271, 2023).